FDFT1 (farnesyl-diphosphate farnesyltransferase 1)
Diseases named in the same sentence as FDFT1 in open-access papers (continued):
Sharing a sentence is not in itself a finding about the gene and the disease.
type 2 diabetes (3 papers, 2009 to 2021). "FDFT1 has been reported to be related to sterol synthesis, which is expected to increase intracellular cholesterol and is associated with type 2 diabetes and coronary artery calcium." (PMID 32626771, 2020).
viral infection (3 papers, 2023 to 2025). "First, we observed that genes that were upregulated in mock-infection vs. input were frequently downregulated in both wild-type and Δvxcl1 virus infections, such as cytokine-encoding Cxcl11, or Fdft1 and Fdps, which are both coding for enzymes in the cholesterol synthesis pathway." (PMID 38077365, 2023). "Genes controlling the key steps in cholesterol biosynthesis, such as FDPS, ACAT2, MVD, LSS, and FDFT1, were transcriptionally commonly suppressed upon viral infection at 48 hpi." (PMID 40857262, 2025). "In addition, we provide evidence that NFE2L2/KEAP1, FDFT1, and AHR are potentially druggable host targets with relevance for various viral infections." (PMID 38319076, 2024).
atherosclerosis (2 papers, 2012 to 2022). A disease characterized by the build-up of fatty material and calcium deposition in the arterial wall resulting in partial or complete occlusion of the arterial lumen. "Using this method, we identified several hepatic regulators related to lipid metabolism (SC5D, LCAT and HMGCR), inflammation (IL1A) and fibrosis (PDGF and COL3A1) that were linked to a set of aorta target genes related to vascular inflammation (TNFA) and atherosclerosis signaling (CCL2 and FDFT1)." (PMID 35897797, 2022). "Gene regulatory network analysis identified specific liver regulators related to lipid metabolism (SC5D, LCAT and HMGCR), inflammation (IL1A) and fibrosis (PDGF, COL3A1), linked to a set of aorta target genes related to vascular inflammation (TNFA) and atherosclerosis signaling (CCL2 and FDFT1)." (PMID 35897797, 2022). "Expression of ABCG5 (control diet) and ABCG8 (regardless of dietary treatment) and expression of HMGCR, FDFT1 and SQLE (regardless of dietary treatment) were significantly higher in the atherosclerosis-resistant than in the atherosclerosis-susceptible strain." (PMID 22682430, 2012).
autoimmune disease (2 papers, 2022 to 2025). A disorder resulting from loss of function or tissue destruction of an organ or multiple organs, arising from humoral or cellular immune responses of the individual to their own tissue constituents. "Our multi-omics data indicate that the SNP rs1047643-linked FDFT1 may be aberrantly activated in B cell development in SLE patients, thereby providing an insight into the genetic implication of lipid metabolism for autoimmune diseases." (PMID 35188103, 2022).
bladder cancer (2 papers, 2022). "FDFT1-associated molecular identification might serve as an alternative or appendage strategy for early prediction of potentially chemoresistant muscle-invasive bladder cancer tissues." (PMID 35093030, 2022). "In bladder cancer specifically, FDFT1 has been suggested as a predictive marker for drug sensitivity to chemotherapy compounds." (PMID 35093030, 2022). "In contrast to these findings, FDFT1 is identified as a tumour suppressor gene in the bladder cancer model." (PMID 35093030, 2022). "Apart from being highly expressed in cisplatin-sensitive bladder cancer cell lines compared to its resistant counterpart, knockdown of FDFT1 in bladder cancer cells has resulted in acquisition of mesenchymal morphology and increased vimentin expression." (PMID 35093030, 2022). "Interestingly, FDFT1 is also among the top 10% genes overexpressed in bladder cancers that are sensitive to the anti-tumour drugs vandetanib and tipifarnib and in esophageal cancer cell lines that are sensitive to docetaxel, paclitaxel, and doxorubicin." (PMID 35093030, 2022). "Farnesyl-diphosphate farnesyltransferase 1 (FDFT1), one of the main regulatory components in cholesterol biosynthesis, may play a role in determining sensitivity towards chemotherapy compounds in bladder cancer." (PMID 35093030, 2022).
colon adenocarcinoma (2 papers, 2023 to 2025). "FDFT1 induces the accumulation of oxygen-reactive species, causing the upregulation of SQS in stages I-III colon adenocarcinoma (COAD)." (PMID 37509391, 2023).
glioma (2 papers, 2017 to 2019). A benign or malignant brain and spinal cord tumor that arises from glial cells (astrocytes, oligodendrocytes, ependymal cells). "Genes in the mevalonate pathway (ACAT2, HMGCS1, and HMGCR) and downstream in the cholesterol biosynthetic pathway (FDPS, FDFT1, and SQLE), were all downregulated in dense NHAs but not dense glioma TS lines." (PMID 28118603, 2017).
non-small cell lung carcinoma (2 papers, 2024 to 2025). A group of at least three distinct histological types of lung cancer, including non-small cell squamous cell carcinoma, adenocarcinoma, and large cell carcinoma. "Analysis of data from the Cancer Cell Line Encyclopedia (CCLE) revealed that the expression levels of HMGCS1, HMGCR, IDI1, FDFT1, and SQLE were significantly higher in SCLC cell lines compared to non-small cell lung cancer (NSCLC) cell lines and other cancer cell lines." (PMID 39669201, 2024).
Parkinson disease (2 papers, 2011 to 2023). A progressive degenerative disorder of the central nervous system characterized by loss of dopamine producing neurons in the substantia nigra and the presence of Lewy bodies in the substantia nigra and locus coeruleus. "We have expanded on the proposed 17q21.31 linkage between SARS-CoV-2 and Parkinson’s disease by identifying 4 variants and 2 pleiotropic genes (i.e. TLK1 and FDFT1) in blood, located outside 17q21.31 and 6p21, that are also associated with both traits." (PMID 37336921, 2023).
Sepsis (2 papers, 2021 to 2024). Sepsis is defined as life-threatening organ dysfunction caused by a dysregulated host response to infection. "Hepatic gene expression of the main regulator of the cholesterol pathway, Srebf2, was increased by sepsis whereas hepatic cholesterol-synthesizing enzymes Hmgcs1 and Fdft1 were unaffected, and Aacs expression was decreased compared to healthy mice—all irrespective of 3HB treatment." (PMID 34274000, 2021).
tongue squamous cell carcinoma (2 papers, 2025). A squamous cell carcinoma that arises from the tongue. "For example, piR-39980 prevents oncogenesis through the repression of FDFT1 expression in tongue squamous cell carcinoma." (PMID 40606680, 2025).
Abdominal obesity (1 paper, 2020). Excessive fat around the stomach and abdomen. "The expression of FDFT1 has been found to be elevated in the visceral fat of individuals with abdominal obesity." (PMID 32443666, 2020).
chronic hepatitis C (1 paper, 2021). "Dysregulation of FDFT1 is associated with many diseases, such as hypoxic injury, nonalcoholic steatohepatitis, and chronic hepatitis C." (PMID 34953498, 2021).
developmental delay (1 paper, 2020). "A recent report highlighted the nerve-related role of FDFT1 in embryogenesis and morphogenesis because a marked reduction of FDFT1 exhibited abnormal clinical features including structural brain malformations, cortical visual impairment, and profound global developmental delay in three patients." (PMID 33113804, 2020).
esophageal cancer (1 paper, 2022). A primary or metastatic malignant neoplasm involving the esophagus. "In liver, lung, prostate, breast, ovary, bladder, cervix, thyroid, and esophageal cancers, FDFT1 is highly expressed, while in colorectal, colon, testicular, uterine, pancreas, and kidney tumours, its expression is downregulated." (PMID 35093030, 2022).
fatty liver disease (1 paper, 2016). A reversible condition wherein large vacuoles of triglyceride fat accumulate in liver cells via the process of steatosis. "Apart from lipids, FDFT1 has been identified in a GWAS on fatty liver disease." (PMID 27286809, 2016).
Hypertension (1 paper, 2023). The presence of chronic increased pressure in the systemic arterial system. "The association between FDFT1 and hypertension could be attributed to its involvement in cholesterol biosynthesis." (PMID 37274792, 2023).
non-alcoholic fatty liver disease (1 paper, 2018). "The locus also encompasses the promoter region of FDFT1, the first enzyme in the cholesterol biosynthesis pathway, which is the substrate for testosterone synthesis, and is associated with non-alcoholic fatty liver disease." (PMID 30566500, 2018).
oesophageal adenocarcinomas (1 paper, 2020). "Northern blot analysis also showed overexpression of FDFT1 mRNA in all six of the amplified oesophageal adenocarcinomas analysed." (PMID 33113804, 2020). "Southern blot analysis of oesophageal adenocarcinomas illustrated FDFT1 to be consistently amplified and overexpressed at 8p22-23 in 12.1% of the tumours analysed." (PMID 33113804, 2020).
pancreatic ductal adenocarcinoma (1 paper, 2023). An infiltrating adenocarcinoma that arises from the epithelial cells of the pancreas. "In addition, using TAK-475, a potent inhibitor of squalene synthase (Fdft1), researcher evaluated the efficacy and tolerability of TAK-475 in a mouse transplant model of pancreatic ductal adenocarcinoma (PDA) and showed significantly reduced tumor growth." (PMID 37089950, 2023).
porokeratosis (1 paper, 2025). A clonal proliferation of abnormal keratinocytes characterized by the development of localized or multiple atrophic skin patches surrounded by an annular keratotic ring called cornoid lamella. "A recent seminal paper from Aki Kubo's group identified FDFT1 as a novel porokeratosis gene, thereby filling a gap in the understanding of the disease mechanism." (PMID 39723554, 2025). "Intriguingly, some FDFT1‐related porokeratosis lesions had an epigenetic alteration characterized by methylation of the FDFT1 promoter." (PMID 39723554, 2025).
renal clear cell cancer (1 paper, 2025). "Furthermore, research indicates that FDFT1 potentially facilitates ferroptosis via the protein kinase B (AKT) signaling pathway in renal clear cell cancer cells, thereby impeding the aggressive progression of these cells." (PMID 40438588, 2025).
Rod-cone dystrophy (1 paper, 2018). An inherited retinal disease subtype in which the rod photoreceptors appear to be more severely affected than the cone photoreceptors. "Homozygosity mapping in combination with WES analysis detected a homozygous missense c.930C>G (p.(Phe310Leu) variant in Farnesyl-Diphosphate Farnesyltransferase 1 (FDFT1) in two siblings from family C with rod-cone dystrophy." (PMID 29320387, 2018).
steatosis (1 paper, 2023). Increased lipid within the cytoplasm of cells. "Fdft1 is one of the causative loci for steatosis, NAS, degree of fibrosis, lobular inflammation, and serum levels of alanine aminotransferase (ALT)." (PMID 37051599, 2023). "Two hub genes Aebp1 and Fdft1 may play important roles in fibrosis and steatosis." (PMID 37051599, 2023).
tumor (38 papers, 2016 to 2025). "Intriguingly, the mevalonate pathway’s downstream effector FDFT1 has recently emerged as a multifunctional oncogenic driver implicated in both tumor progression and therapy resistance." (PMID 40722703, 2025). "In contrast, invasion, migration, and metastasis of cells are significantly inhibited by loss of function or inhibition of FDFT1, and the number of lung metastases is markedly decreased in mice carrying FDFT1-knockdown tumours." (PMID 33113804, 2020). "The low expression of FDFT1 was significantly associated with tumour size, histological type, lymph node metastasis, tumour differentiation, invasion, malignant progression, and higher TNM stage." (PMID 33113804, 2020). "FDFT1 has been implicated in cancer, both as a potential oncogene and as a potential tumour suppressor gene." (PMID 33113804, 2020). "Therefore, decreased expression of FDFT1 is associated with tumor cell growth and progression and poor prognosis in CRC." (PMID 38023258, 2023). "Chemoresistance and tumour progression may involve farnesyl-diphosphate farnesyltransferase 1 (FDFT1), a gene that encodes the membrane-associated enzyme squalene synthase, which is the first specific enzyme in cholesterol biosynthesis." (PMID 35093030, 2022). "FDFT1 is a gene that encodes the membrane-associated enzyme squalene synthase, which is the first specific enzyme in cholesterol biosynthesis that is increasingly implicated in tumour progression and the development of therapeutic resistance to anticancer drugs." (PMID 35093030, 2022). "However, its role in tumour progression is cancer-specific: FDFT1 has been implicated as a potential oncogene and as a tumour-suppressive gene in different types of cancer." (PMID 35093030, 2022). "Although research has identified a correlation between accelerated cholesterol metabolism and the progression of cancer, the role of FDFT1 as a tumor suppressor or as a potential oncogene remains ambiguous." (PMID 40438588, 2025). "Sirius Red and Ki67 staining also revealed that FDFT1 knockdown suppressed the proliferation of tumor cells." (PMID 39899681, 2025). "Functionally, FDFT1 knockdown inhibited tumor growth and metastasis, whereas FDFT1 overexpression promoted tumor growth and metastasis in vivo and in vitro." (PMID 39899681, 2025). "Fasting also upregulated the expression of the farnesyl-diphosphate farnesyltransferase 1 (FDFT1) as a tumor suppressor and cholesterogenic gene." (PMID 38023258, 2023). "Other experiments showed decreased tumor volume and size when knocking down FDFT1 due to removing squalene accumulation." (PMID 37509391, 2023). "Meanwhile, the protein expression levels of FDFT1 was notably down-regulated, accompanied by the alteration of critical biomarkers of the cell cycle, autophagy, apoptosis, and ferroptosis in the tumor tissues from the ATA-treated mice." (PMID 37834468, 2023). "Meanwhile, the expression of FDFT1 and marker proteins for the cell cycle, apoptosis, ferroptosis, and autophagy in tumor tissues was detected through Western blotting." (PMID 37834468, 2023). "Of note, ATA remarkably suppressed the growth of HCT116 xenografts in nude mice and displayed an apparent attenuation of FDFT1 in tumor tissues accompanied by the alteration of the biomarkers of autophagy, cell cycle, apoptosis, and ferroptosis." (PMID 37834468, 2023). "Here, we briefly review how cholesterol is synthesised, how cancer cells reprogram cholesterol metabolism to promote carcinogenesis and treatment resistance to chemotherapy, and the emerging role of FDFT1 in tumour progression and chemoresistance." (PMID 35093030, 2022). "It has been confirmed by a study that downregulated FDFT1 is related to late tumor progression and worse prognosis in CRC, and FDFT1 suppresses the tumorigenesis through negative regulation of AKT/mTOR/HIF1α signaling pathway." (PMID 36160009, 2022).
tumor (continued). "In tumours where FDFT1 is downregulated, isoprenoids can accumulate, providing more substrate for protein prenylation, causing uncontrolled cell growth." (PMID 35093030, 2022). "Our findings demonstrated that FDFT1 acted as a tumor suppressor and upregulation of FDFT1 expression attenuated GC proliferation, migration and invasion." (PMID 34953498, 2021). "In contrast genes involved in development and differentiation (Arid5b, Inmt, Grem2, Gdap10), cell metabolism (Alas1, Gsta1, Thrsp, Fdft1, Elovl6), tumor growth (SerpinA4, Cish, Rpl36), and cell cycle control (PLK3, Myc, HNF6/Onecut1) were downregulated." (PMID 33004985, 2020). "One of the mechanisms by which FDFT1 promotes tumour growth and proliferation involves enhanced cholesterol biosynthesis." (PMID 33113804, 2020). "Inhibition of FDFT1 in tumour-bearing mice by zaragozic acid decreased cholesterol leading to reduced oxysterol levels within the TME." (PMID 33113804, 2020). "In this review, we outline the role of cholesterol in cancer and, in this context, look at the role of FDFT1 in both tumours and TME." (PMID 33113804, 2020). "These considerations are likely to provide plausible explanations for why FDFT1 acts as an oncogenic gene in some cancers and a tumour suppressor in others." (PMID 33113804, 2020). "Most studies have reported that the upregulation of FDFT1 is required for tumour progression, as cholesterol is necessary for cell proliferation, and lipid rafts for signalling transduction, invasion, and migration of cancer cells." (PMID 33113804, 2020). "An underlying dependence of CR tumor cells for energy metabolism pathways such as enhanced expression of GLDC, ACC, ASNS, FDFT1, UGDH, PYCR2, etc was noted." (PMID 27470985, 2016). "Notably, FDFT1 knockdown was still effective at 22 weeks and significantly relieved the tumor burden, as evidenced by the decreases in tumor number, liver/body ratio, and tumor maximum diameter in the FDFT1‐knockdown group." (PMID 39899681, 2025). "Interestingly, we found that FDFT1 expression was heterogeneous in tumor tissues, although it was generally expressed at higher levels in tumors than in nontumor tissues." (PMID 39899681, 2025). "Interestingly, the effect of FDFT1 on cancer is heterogeneous, serving opposite roles in different tumor cells." (PMID 40438588, 2025). "Additionally, Ki67 staining indicated that AZD5363 inhibited tumor proliferation, and this effect was more pronounced when FDFT1 inhibition was combined with AZD5363 treatment." (PMID 39899681, 2025). "Moreover, we found that FDFT1 expression was positively correlated with tumor size, distant metastasis, and Barcelona Clinic Liver Cancer (BCLC) and negatively correlated with overall survival." (PMID 39899681, 2025). "Importantly, FDFT1 inhibition combined with AZD5363 treatment markedly suppressed the tumor growth in vivo." (PMID 39899681, 2025). "However, while FDFT1 acts as a tumor suppressor by negatively regulating AKT/mTOR/HIF1α signaling in CRC cells, SQLE activates the β‐catenin oncogenic pathway." (PMID 38517197, 2024). "Additionally, loss of heterozygosity, as well as homozygous deletions in a variety of human cancer cell lines and tumours imply that there are several tumour-suppressor genes on chromosome arm 8p, specifically at the 8p22-23.1 region, where FDFT1 resides." (PMID 33113804, 2020). "Besides, new ideas are needed to explain why FDFT1 appears to act as an oncogene in some cancers and as a tumour suppressor in other cancers." (PMID 33113804, 2020). "However, it is also necessary to consider the role of FDFT1 in terms of the importance of the tumour microenvironments (TME), which has been recognized due to recent immune checkpoint blockers." (PMID 33113804, 2020). "Furthermore, in tumor xenograft models, FDFT1 inhibition significantly impaired tumor formation and reduced tumor weight, whereas FDFT1 overexpression increased tumor volume and weight." (PMID 39899681, 2025).